CCNG2 (cyclin G2)
Diseases named in the same sentence as CCNG2 in open-access papers (continued):
Sharing a sentence is not in itself a finding about the gene and the disease.
cancer (continued). "Consistent with its tumor suppressive role, which has been associated with lower CDK2 protein levels, the expression of CCNG2 is downregulated in several human cancers, and correlates with a worse clinical prognosis." (PMID 31420702, 2020). "The patient data showed a significant decrease in cyclin G2 expression through advanced cancer stages." (PMID 33240810, 2020). "While this study is the first on EOC cells to show that CCNG2 is targeted by a miRNA, several studies on other types of cancer have reported that miRNAs can target CCNG2 to promote cancer development." (PMID 31013711, 2019). "Recent data has shown that cyclin G2 (CCNG2) is an atypical cyclin that inhibits cell cycle progression and is often dysregulated in human cancers." (PMID 30420966, 2018). "It has been reported that cyclin G2 is abnormally expressed in many types of cancers and is an apoptosis regulator, but its mechanisms in cancer progression remain elusive." (PMID 30547803, 2018). "Increasingly, the evidence suggests that CCNG2 is crucially involved in human cancer signaling pathways." (PMID 25888956, 2015). "Therefore, we propose to inject lentiviruses or preparations (overexpressing cyclin G2) into the tumor of patients to make cancer cells and macrophages overexpress cyclin G2, then combine IFN-γ or IFN-γ + PD-1 inhibitor to suppress tumor." (PMID 36566226, 2022). "Cyclin G2 functions as a tumor suppressor in various cancer cells; however, its role in macrophages remains unclear." (PMID 36566226, 2022). "Cyclin G2 is a tumor suppressor and has a low expression in several cancers." (PMID 33240810, 2020). "For example, the expression of miR-1246 was significantly correlated with chemoresistance and cancer stem-cell-like characteristics and could identify a worse prognosis in cancer patients (pancreatic) by targeting cyclin G2 protein-coding genes such as CCNG2." (PMID 33050659, 2020). "Moreover, CCNG2 inhibits cancer stem cell-like properties and suppresses the epithelial-to-mesenchymal transition by attenuating Wnt signaling." (PMID 31420702, 2020). "Several studies indicate that CCNG2 may have an inhibitory role in the progression of cancer as lower expression of CCNG2 is often found in more aggressive cancers, including thyroid." (PMID 30429236, 2019). "However, there are few reports on the identity of pathways and the precise mechanisms that mediate the roles of cyclin G2 in gastric tumorigenesis and other cancers." (PMID 30547803, 2018). "The cyclin family protein CCNG2 has an important inhibitory role in cancer initiation and progression, but the exact mechanism is still unknown." (PMID 29720957, 2018). "Indeed, overexpression of cyclin G2 inhibits proliferation in many cell lines, and an inverse relationship is observed between cyclin G2 levels and cancer progression." (PMID 28640887, 2017). "Therefore, we speculate that cyclin G2 knockout in macrophages may affect the progression of more cancer types." (PMID 36566226, 2022). "In addition, macrophage cyclin G2 may be a biomarker for treatment sensitivity and prognosis during the selection of cancer patients for immunotherapy." (PMID 36566226, 2022). "High levels of this miRNA are correlated with resistance to gemcitabine treatment in PC cells promoting PC metastasis, invasion, cancer stemness, and angiogenesis via inhibition of CCNG2 (clinical significance of cyclin G2) expression." (PMID 34205944, 2021). "Cyclin G2 (CCNG2) is an atypical cyclin that inhibits cell cycle progression and is often dysregulated in human cancers." (PMID 31978940, 2020). "Cyclin G2 (CCNG2) is an atypical cyclin that functions to inhibit cell cycle progression and is often dysregulated in human cancers." (PMID 28640887, 2017). "Given that cyclin G2, a binding partner of PP2A, has been shown to be upregulated in cancer cells in response to hypoxic conditions, we studied its temporal expression pattern in relation to PP2A activity following exposure to hypoxia." (PMID 22253878, 2012).
cancer (continued). "CCNG2 is a cyclin with a role in cell-cycle regulation in normal and cancer cells, but no specific role has been described in regulating inflammation or the immune system thus far." (PMID 37510214, 2023). "In CRC miR-1246 inhibits Gal-9 and CCNG2, which is a tumor suppressor; decreased expression of CCNG2 occurs in many types of cancer and correlates with lymph node metastasis, clinical stage, and poor prognosis." (PMID 36012588, 2022). "Moreover, the PT complex upregulated the expression of specific potential cancer suppressor genes, such as cyclin G2, V-set and transmembrane domain containing 4 (VSTM4), coiled-coil domain containing 149 (CCDC149), CD2 molecule, and cyclin G2." (PMID 38027033, 2023). "Previously, we reported that cyclin G2 inhibited the osteogenesis of murine myoblast C2C12 cells through the canonical Wnt signaling; this suggested that cyclin G2 may play a role in other types of cells, including cancer cells." (PMID 30547803, 2018). "However, the exact role that cyclin G2 plays in OSCC and other cancers is still unknown." (PMID 33240810, 2020).
tumor (40 papers, 2005 to 2026). "Of note, the overexpression of the tumor suppressor CCNG2/Cyclin G2 is associated with the activation of autophagic flux and increased levels of ATG5, ATG7 and Beclin." (PMID 37626880, 2023). "While ALDH1A1 and MYC genes were reported in metastasis of several tumor types and associated with poor prognosis, for CCNG2, a cell cycle checkpoint cyclin upregulated in response to DNA damage, the association to stemness was not clear." (PMID 28938627, 2017). "BHLHE40 encoding DEC1 mediates cellular senescence by its direct target gene CCNG2, that encodes the atypical and tumor suppressive Cyclin G2, as a novel tumor suppressive axis encompassing androgen receptor-BHLHE40-Cyclin G2 in order to mediate cellular senescence in PCa cells." (PMID 38902772, 2024). "Moreover, the decreased expression of cyclin G2 was significantly associated with high tumor size (P < 0.01), poor tumor differentiation (P < 0.05) as well as metastasis status (P < 0.05)." (PMID 30547803, 2018). "CEBPB was identified as highly expressed in dormant tumor cells, where it maintained tumor dormancy by transcriptionally activating cell cycle negative regulators, particularly CCNG2." (PMID 41799200, 2026). "The cyclin family protein CCNG2 acts as a tumor suppressor gene through its regulation of cell proliferation." (PMID 40570725, 2025). "Previous studies have shown that CCNG2 can inhibit the Wnt/β-catenin signaling pathway, thereby affecting tumor progression." (PMID 40135235, 2025). "CCNG2 has been reported in various types of tumors as a potential tumor suppressor and holds promise as a prognostic biomarker." (PMID 40135235, 2025). "To assess PAGln’s effect on the Wnt/β-catenin signaling pathway in vivo, we conducted q-PCR analysis of CCNG2 expression in subcutaneous tumor tissues." (PMID 40135235, 2025). "Further analysis showed that CCNG2 and CHSY1 were significantly associated with the tumor immune microenvironment." (PMID 40570725, 2025). "Further, RNA-seq and ChIP-seq analysis indicate that the atypical tumor suppressive cyclin G2 emerged as a novel downstream target of BHLHE40 and a mediator of SAL-induced cellular senescence." (PMID 38902772, 2024). "This variant was associated with the differential expression of LINC01094 in eQTL analysis using normal colon mucosa samples (p = 0.0025) and CCNG2 in tumor tissue samples (p = 0.024)." (PMID 38664626, 2024). "Cyclin G2 (CCNG2) is modulated via the cell cycle and serves as a tumor-suppressor gene and its expression is drastically diminished in BC." (PMID 37067729, 2023). "Unlike other cyclins, which positively regulate the cell cycle, cyclin G2 (CCNG2) regulates cell proliferation as a tumor suppressor gene." (PMID 37204480, 2023). "Mouse tumor models were used to determine the effect of cyclin G2 in macrophages on tumor growth in vivo following IFN-γ treatment." (PMID 36566226, 2022). "Preliminary studies by our group have shown that cyclin G2 acts as a tumor suppressor in various tumor cells." (PMID 36566226, 2022). "Our findings define a new function for cyclin G2 in macrophages — regulating CTLs and tumor angiogenesis." (PMID 36566226, 2022). "Cyclin G2 inhibited tumor angiogenesis and promoted the recruitment of CTLs by increasing the release of CXCL9 from macrophages." (PMID 36566226, 2022). "Our elucidation of the antitumor function and mechanisms of cyclin G2 in macrophages provides a new theoretical basis for the development of tumor therapy." (PMID 36566226, 2022). "Overexpression of cyclin G2 reduced the tumor-infiltrating Tregs and dramatically shifted the balance in favor of IFN-γ + CD4 + and IFN-γ + CD8 + T cells over Tregs in tumors." (PMID 34452627, 2021). "Mice harboring GL261-OE showed impeded tumor growth, whereas cyclin G2 overexpression combined with α-PD-1 manifested the smallest tumor volume and lightest weight." (PMID 34452627, 2021).
tumor (continued). "Taken together, we concluded that cyclin G2 exerts its tumor suppressor functions by regulating lactate secretion." (PMID 34452627, 2021). "Using the bioinformatics tool, we identified CCNG2 mRNA as one of the putative targets of miR-17-5p due to its involvement in the inhibition of tumor proliferation and cell cycle." (PMID 34598688, 2021). "Combined cyclin G2 overexpression with α-PD-1 treatment exhibited the highest survival rate owing to the efficient synergistic effect on tumor inhibition." (PMID 34452627, 2021). "The cyclin G2 gene (CCNG2) has also been reported to display several repressive actions on EOC-derived tumour cell lines." (PMID 33080952, 2020). "More recently, we found that CCNG2 inhibited epithelial-to-mesenchymal transition, cell migration, invasion, and spheroid formation in vitro, as well as tumor formation and metastasis in vivo." (PMID 31013711, 2019). "We also identified that a major mechanism by which CCNG2 exerted these anti-tumor effects was via disrupting Wnt/β-catenin signaling." (PMID 31013711, 2019). "Overexpression of cyclin G2 remarkably suppressed tumor growth, as reflected by tumor volume and weight, compared with the blank group (without any transfection) and GFP vector control (NC) group cells." (PMID 30547803, 2018). "Among those putative target candidates, five potential tumor suppressors, including CCNG2, FOXP1, NRG1, LRIG1, and TNFSF10, were shown to have a direct binding site with miR-130b-5p." (PMID 25888956, 2015). "Induction of CCNG2 is confirmed in CRPC tumor spheroids and xenograft tumors of treated mice." (PMID 40368177, 2025). "Downregulation was observed for the genes CCNG2 (−9.0-fold), CCND1 (−5.84-fold), TFDP1 (−5.84-fold), CDC34 (−5.14-fold), and HUS1 (−4.52-fold), which are normally linked to the development of various tumor types when overexpressed." (PMID 39337305, 2024). "In the present study, we investigated how cyclin G2 in macrophages could alter the immunosuppressive tumor microenvironment during the IFN-γ reprogramming of macrophages." (PMID 36566226, 2022). "We also found that cyclin G2 could inhibit tumor angiogenesis after IFN-γ stimulation of macrophages." (PMID 36566226, 2022). "Therefore, identifying treatments that can modify the tumor microenvironment through cyclin G2 is worth further study." (PMID 36566226, 2022). "Therefore, the tumor suppressive effects of cyclin G2 are mediated through its regulation of CXCL9 secretion from macrophages under the action of IFN-γ." (PMID 36566226, 2022). "We, therefore, hypothesized whether cyclin G2 affects immune cell composition during tumor regression in residual tumors." (PMID 34452627, 2021). "Age, sex, and tumor size were not correlated with the expression of cyclin G2, whereas the clinical stage was associated with cyclin G2 expression (P < 0.05)." (PMID 33240810, 2020). "Taken together, these results indicated that cyclin G2 functioned as a tumor suppressor in OSCC through its interaction with IGFBP3 and the subsequent blockage of the connection between integrin and IGFBP3, the phosphorylation of FAK and the FAK-SRC-STAT signaling pathways." (PMID 33240810, 2020). "The cell cycle protein cyclin G2 is considered a tumor suppressor." (PMID 33240810, 2020). "Therefore, it is likely that FOXO3 exerts anti-tumor effects on EOC cells in part by inducing CCNG2 expression." (PMID 31013711, 2019). "Cyclin G2 (CCNG2), a protein encoded by the CCNG2 gene, belongs to a group of unconventional cyclins that play a role in maintaining cellular quiescence and cell cycle arrest, and has tumor suppressive effects in EOC." (PMID 31013711, 2019). "Therefore, CCNG2 is often proposed to be a tumor suppressor gene through its regulation of cell proliferation." (PMID 29720957, 2018). "Moreover, overexpression of cyclin G2 attenuated tumor growth and metastasis both in vitro and in vivo." (PMID 30547803, 2018).
tumor (continued). "Furthermore, the number of apoptotic cells, as determined by a TUNEL assay, was increased in tumor cells overexpressing CCNG2." (PMID 29720957, 2018). "Increasing evidence suggests that cyclin G2 acts as a tumor suppressor." (PMID 28640887, 2017). "The ability of miR-130b-5p to repress CCNG2 expression may enhance malignancy by accelerating cell cycle transition in triple-negative tumor cells." (PMID 25888956, 2015). "Cyclin G2 was also upregulated in Ta tumours compared to normal tissue." (PMID 16052224, 2005). "Therefore, we speculate that overexpression of cyclin G2 in macrophages can enhance effect of IFN-γ treat tumor, which may be a potential therapeutic scheme." (PMID 36566226, 2022). "Cyclin G2 is an unconventional cell cycle protein encoded by the CCNG2 gene that plays a negative role in the cell cycle process.Thus, it also plays an important role in the biological functions of cell growth inhibition and tumor suppression." (PMID 33240810, 2020). "Furthermore, BMI-1 and CCNG2 levels evolved inversely during CML progression, suggesting that BMI-1 could support acute transformation of CML through the silencing of a CCNG2-mediated tumor-suppressive autophagy response." (PMID 29466292, 2018). "These EVs transfer miR-1246 to recipient cells and thereby suppress Cyclin-G2 (CCNG2), a tumor-suppressor gene that regulates cell proliferation." (PMID 40182121, 2025). "CCNG2 is upregulated in macrophages by IFN-γ, which enhances the chemotaxis of cytotoxic T lymphocytes (CTLs) and inhibits angiogenesis to suppress tumor growth." (PMID 40135235, 2025). "Cyclin G2 inhibits the Warburg effect by blocking LDHA Y10 phosphorylation, thereby reversing the immunosuppressive microenvironment and halting tumor progression with a stronger anti-tumor effect when combined with anti-PD-177." (PMID 39897050, 2025). "Since the KD of BHLHE40 significantly reduces the CCNG2 mRNA it suggests that BHLHE40 up-regulates CCNG2 expression and the atypical CCNG2 is part of the BHLHE40 tumor suppressive pathway." (PMID 38902772, 2024). "Cyclin G2 is upregulated by IFN-γ in macrophages, promotes the secretion of CXCL9 to increase CTL chemotaxis and inhibit angiogenesis to suppress tumor growth." (PMID 36566226, 2022). "We found that it can upregulate cyclin G2 protein expression in macrophages, and cyclin G2 activates the IFN-γ-STAT1 signaling pathway, thereby affecting the tumor microenvironment." (PMID 36566226, 2022). "We found that cyclin G2 plays a critical role in the recruitment of CTLs by IFN-γ-stimulated macrophages, thereby remodeling the tumor microenvironment." (PMID 36566226, 2022). "We found that cyclin G2 increased CXCL9 production and secretion from macrophages after IFN-γ treatment, which could explain the effects of cyclin G2 on CTL recruitment and tumor angiogenesis." (PMID 36566226, 2022). "Here, we reveal that macrophage cyclin G2 alters the tumor microenvironment after IFN-γ treatment, suggesting that targeting cyclin G2 may be helpful for treating tumors." (PMID 36566226, 2022). "Therefore, since most lactate in the TME was generated from tumor cells, we chose C57BL/6 WT inoculated with GL261 cells stably expressing cyclin G2." (PMID 34452627, 2021). "More importantly, we verified miR-17-5p negatively regulated CCNG2 mRNA and protein expression by directly targeting its 3’UTR, indicating that miR-17-5p might act as a tumor promoter in HNSCC." (PMID 34598688, 2021). "Overexpression of cyclin G2 generated immune-favorable TME, evident by the reduced proportion of Tregs and elevated tumor-infiltrating IFN-γ + CD4 + and IFN-γ + CD8 + T cells, as well as low levels of immunosuppressive cytokines and elevated cytotoxic cytokines." (PMID 34452627, 2021). "Expression of CNTD1, CNTD2 CCNG2, or SPY1 was undetectable in the tumor or normal cells." (PMID 28860486, 2017).
tumor (continued). "In line with this possibility, our findings suggest that aggressive tumor cells with increased expression of PTOV1, ALDH1A1, and CCNG2 might correspond to potential CSCs with great capacity to metastasize and higher resistance to docetaxel." (PMID 28938627, 2017). "The other six genes with more than two-fold upregulation in more than five tumours arrayed were CCNG2 in 30 tumours, NDRG1 in 18 tumours, PFKFB3 in 17 tumours, RNAse4 in 10 tumours, Adrenomedullin (ADM) in eight tumours and Glucose transporter 1 (GLUT-1) in six tumours." (PMID 16052224, 2005). "Furthermore, miR-1246 binds to the 3′UTR of Cyclin-G2(CCNG2) thereby directly targeting CCNG2 expression and leading to the downregulation in the expression of the tumour suppressor gene in non-malignant HMLE cells." (PMID 38455764, 2024). "The atypical cyclin CCNG2 (Cyclin G2) acting as a tumor suppressor, is identified here as a novel downstream direct target gene of both BHLHE40 and AR by ChIP-seq and RNA-seq to mediate SAL-induced cellular senescence and linking clock genes with tumor suppression." (PMID 38902772, 2024). "The HIF‐1α target genes Vegf, Snai1, and Ccng2 showed reduced expression upon nAb‐CCL2 treatment in the CD group, although this did not lead to significant tumor suppression." (PMID 41160815, 2026). "Interestingly, CPT treatment significantly upregulated SHH, an oncogene that promotes the progression and metastasis in PDAC, but downregulated CCNG2, a key tumor suppressor gene in PDAC, suggesting a pro-tumor activity of Vitamin D in MiaPaca2 cells without epigenetic priming." (PMID 38272889, 2024).
infection (2 papers, 2018 to 2024). The state of being infected such as from the introduction of a foreign agent such as serum, vaccine, antigenic substance or organism. "Upon infection, a distinct phenotype (subcluster 7.1) emerged among infected cells that shared markers with the highly infected cluster 4, including CITED2, FOS, TXNIP, and CCNG2 genes." (PMID 38896609, 2024).
CCNG2 also shares sentences with these, for which no sentence is quoted: bladder cancer (3 papers); rectal cancer (2); fibrosis (1); gastric adenocarcinoma (1); hepatocellular carcinoma (1); lymph node metastasis (1); lymphoma (1); mantle cell lymphoma (1); nasopharyngeal carcinoma (1); renal cell carcinoma (1); sarcoma (1); thyroid cancer (1).